TYRP1 (tyrosinase related protein 1)
Diseases named in the same sentence as TYRP1 in open-access papers (continued):
Sharing a sentence is not in itself a finding about the gene and the disease.
cutaneous melanoma (7 papers, 1998 to 2025). A primary melanoma arising from atypical melanocytes in the skin. "Thus, TYRP1 mRNA and Tyrp1 protein expressions in cutaneous melanoma metastases remain associated with prognostic features of the corresponding primary lesions, regardless of the interval between the diagnosis of the primary and the occurrence of the cutaneous metastases." (PMID 22045183, 2011). "First, we built panels of uveal and acral melanoma cell lines and compared the levels of TYRP1 expression to cutaneous melanoma cell lines with high (M249) and intermediate (M202 and M229) TYRP1 expression." (PMID 38336975, 2024). "The prevalence of TYRP1 expression (>1%) in cutaneous melanoma observed in this study was in the same range as the prevalence in metastatic cutaneous melanoma samples from an in-house internal tissue bank (n = 51), analyzed with the Ventana EPR13063 investigational IHC assay (70% vs 66%)." (PMID 38577337, 2024).
breast carcinoma (6 papers, 2017 to 2026). "This genome-wide association study, however, identified TYRP1 (rs41302073), a melanin synthesis regulatory gene, as a significant risk allele for breast cancer in their dataset that included African American and Barbadian women." (PMID 33659210, 2020).
uveal melanoma (6 papers, 2023 to 2025). A melanoma derived from melanocytes of the uveal tract. "We develop a highly sensitive CAR-T cell therapy that detects surface TYRP1 in tumor cells with high TYRP1 overexpression and presents antitumor activity in vitro and in vivo in murine and patient-derived cutaneous, acral and uveal melanoma models." (PMID 38336975, 2024). "TYRP1 is also highly expressed in tumors derived from melanocytes such as in cutaneous and uveal melanomas." (PMID 37946423, 2024). "Approximately 60% of patients with acral and mucosal melanoma and ~90% of patients with uveal melanoma overexpress TYRP1, and TYRP1 CAR-T cell therapy could potentially lead to clinical benefit in this patient subset." (PMID 38336975, 2024). "For uveal and mucosal melanoma, other groups have reported different prevalence values than our study (~60% for uveal melanoma and ~90% for sinonasal mucosal melanoma); however, different TYRP1 assays were used in those studies and only primary tumor samples were analyzed." (PMID 38577337, 2024). "In a phase I clinical trial, the vesicular stomatitis virus (VSV) expressing interferon beta (IFN-β) and tyrosinase-related protein 1 (TYRP1) demonstrated safety and induced dose-dependent immunogenicity and T-cell responses in uveal melanoma." (PMID 39881333, 2025). "In uveal melanoma, the five cell lines in our panel (MP65, MP38, MP41, MP46, MM28) presented high TYRP1 expression." (PMID 38336975, 2024). "Here, the authors show TYRP1 as a target for CAR-T cell therapy in preclinical models of cutaneous, acral and uveal melanoma." (PMID 38336975, 2024). "Interestingly, 59%, 60%, and 92% of patients with acral, mucosal, and uveal melanoma, respectively, present high expression of TYRP1 (Log2 FPKM ≥ 7) and could benefit significantly from a T-cell therapy designed to target TYRP1." (PMID 38336975, 2024). "Based on the clinical success of tebentafusp and our preclinical results, we anticipate that the TYRP1 CAR-T cell therapy has the potential to benefit patients with uveal melanoma and overcome the HLA restriction, providing a clinical candidate for ~90% of patients with uveal melanoma." (PMID 38336975, 2024).
skin cancer (4 papers, 2016 to 2025). "By controlling pigmentation genes (e.g., TYR, TYRP1, and TYRP2), MITF is the main modulator of melanogenesis in response to environmental stimuli and was also proposed to exert an oncogenic role in several skin cancers." (PMID 32438927, 2020).
melanosis (3 papers, 2013 to 2023). "TYRP1, MC1R, and GPR143 genes are thought to play an important role in the process of melanosis in chickens." (PMID 37235424, 2023).
Nystagmus (3 papers, 2014 to 2019). Rhythmic, involuntary oscillations of one or both eyes related to abnormality in fixation, conjugate gaze, or vestibular mechanisms. "In patient NYS-009, with clinical diagnosis of IIN but with genetic diagnosis of TYRP1, interestingly we noted both horizontal and vertical nystagmus." (PMID 28378818, 2017). "Nystagmus is also not observed in dogs with TYRP1 mutations." (PMID 24647637, 2014). "Proband 8 also has a 1-year-old brother with nystagmus who was also homozygous for TYR p.(Arg402Gln) and TYR p.(Ser192Tyr) but did not carry the TYRP1 p.(Ala70Thr) variant." (PMID 31719542, 2019).
autoimmune disease (2 papers, 2023 to 2024). A disorder resulting from loss of function or tissue destruction of an organ or multiple organs, arising from humoral or cellular immune responses of the individual to their own tissue constituents. "VKH disease is an autoimmune disease, in which tyrosinase and tyrosinase-related protein-1 and -2 of melanocytes are primarily identified as autoantigens." (PMID 38137811, 2023).
brain tumor (2 papers, 2017 to 2023). "The other missenses mutations in TYRP1 (c.C785T, p.T262M) and WRN (c.G1149T: p.L383F, and c.G2983A: p.A995T) were present in a heterozygous state in the patient and his brother with a brain tumor, while it was absent in the unaffected brother." (PMID 38028607, 2023).
Hermansky-Pudlak syndrome (2 papers, 2017). Hermansky-Pudlak syndrome (HSP) is a multi-system disorder characterized by oculocutaneous albinism, bleeding diathesis and, in some cases, neutropenia, pulmonary fibrosis, or granulomatous colitis. "OCA can be caused by TYR, TYRP1 or MATP gene mutation; GS may be caused by pathogenic variants in MYO5A, RAB27A or MLPH; at least nine subtypes of hermansky-pudlak syndrome (HPS), HPS2 caused by variants in AP3B1 which most closely resembles CHS." (PMID 28145517, 2017).
lung carcinoma (2 papers, 2022 to 2024). "Yet, the proportion of samples exhibiting high levels of both TYRP1 and CD3D samples was comparatively low in SKCM relative to the lung cancers." (PMID 39943991, 2024).
ocular albinism type 1 (2 papers, 2005 to 2019). "Six genes are associated with autosomal recessive OCA (TYR, OCA2, TYRP1, SLC45A2, SLC24A5 and LRMDA), and one gene, GPR143, is associated with X-linked ocular albinism (OA)." (PMID 30679655, 2019).
oculocutaneous albinism type 1 (2 papers, 2017 to 2023). Type 1 oculocutaneous albinism (OCA1) describes a group of tyrosine related OCAs that includes OCA1A, OCA1B, type 1 minimal pigment oculocutaneous albinism (OCA1-MP) and type 1 temperature sensitive oculocutaneous albinism (OCA1-TS). "It has been suggested that mutations in tyrosine (TYR) and tyrosinase-related enzyme 1 (TYRP1) may cause human oculocutaneous albinism type 1 (OCA1) and type 3 (OCA3)." (PMID 37235424, 2023).
pigment dispersion syndrome (2 papers, 2010 to 2014). Pigment-dispersion syndrome is an eye disorder that occurs when pigment granules that normally adhere to the back of the iris (the colored part of the eye) flake off into the clear fluid produced by the eye (aqueous humor). "Inbred mice of the D2 strain spontaneously develop pigment dispersion syndrome due to a synergistic effect in mutations of the Gpnmb and Tyrp1 genes." (PMID 24621581, 2014).
pigmentary glaucoma (2 papers, 2006 to 2025). Pigmentary glaucoma is a type of secondary open-angle glaucoma characterized by heavy homogenous pigmentation of the trabecular meshwork, iris transillumination defects, and pigment along the corneal endothelium (Krukenberg spindle). "Specifically, we used DBA/2J mice, a strain characterized by mutations in the Tyrp1 and Gpnmb genes that impair melanosome function, leading to pigment dispersion in the iris and contributing to the development of pigmentary glaucoma." (PMID 40806647, 2025).
choroidal melanoma (1 paper, 2008). Malignant tumor of melanocytes of the choroid. "Although the Tyrp1-TAg transgenic mouse model of pigmented ocular neoplasm cannot be strictly considered as a choroidal melanoma, it has many features found in human choroidal melanoma." (PMID 18958307, 2008). "We have studied the transgenic mouse strain, Tyrp-1-TAg, to try to gain insight into possible molecular mechanisms common to pigmented ocular neoplasms occurring spontaneously in the eyes of these mice and human choroidal melanoma." (PMID 18958307, 2008).
eyelid coloboma (1 paper, 2023). "Using selective sweep analysis, we found that PTPRM on chromosome Z influences the upper eyelid coloboma phenotype of the Huoyan goose, and TYRP1 is a plausible candidate gene for the Huoyan gosling feather color." (PMID 38066959, 2023).
keloid (1 paper, 2016). An irregularly shaped, elevated mark on the skin caused by deposits of excessive amounts of collagen during wound healing. "Further, many of the vimentin-positive cells located near the BMZ in keloid scars, adjacent to gaps in integrin α6 staining, were positive for the melanocyte-specific protein tyrosinase-related protein 1 (TYRP1), indicating these cells are melanocytes." (PMID 27574697, 2016).
ocular neoplasms (1 paper, 2008). "Interestingly, in triplicate experiments using semi-quantitative PCR and western blotting to compare ocular tumors in Tyrp-1 mice with WT eyes at the same age, we found that ETS-2 mRNA levels were higher than ETS-1 mRNA levels, but ETS-1 protein levels were higher than ETS-2 protein levels." (PMID 18958307, 2008).
oculocutaneous albinism type IA (1 paper, 2015). "The combination of tools resulted in the indication of four, two and one nsSNPs as the most deleterious mutations in the TYR, TYRP1 and P proteins of the gene, which are associated with oculocutaneous albinism type IA (OCA1A), type III (OCA3) and type II (OCA2), respectively." (PMID 25794181, 2015).
triple-negative breast carcinoma (1 paper, 2025). An invasive breast carcinoma which is negative for expression of estrogen receptor (ER), progesterone receptor (PR), and human epidermal growth factor receptor 2 (HER2). "A Venn diagram further identified three potential key TRGs in triple-negative breast cancer (TNBC), namely ADH1A, AOC2, and TYRP1." (PMID 41006587, 2025).
tumor (107 papers, 2005 to 2026). "TYRP1 functions in melanin synthesis, although high expression is associated with a poor prognosis due to sequestration of the tumour suppressor miRNA-16." (PMID 37511580, 2023). "Since the B16F10 model is immunologically cold and unresponsive to most single-agent immunotherapies, we combined our immunocytokine treatment with TA99, a murine IgG2a tumor-targeting antibody against tumor-associated antigen tyrosinase-related protein-1." (PMID 36712341, 2022). "The molecular bases of the association of MGRN1, PMEL, MLANA, and TYRP1 expression within the tumor and patient survival remain speculative." (PMID 40004203, 2025). "Furthermore, TYRP1 mRNA has been proven to cause ncRNAs to function as sponges for miR-16, which is known for its tumor-suppressor function in STAD." (PMID 36241983, 2022). "Our observations suggest that virotherapy led to epitope spreading in which T cell responses against additional tumor associated antigens was induced, and that VSV-IFNβ-TYRP1 may induce some level of anti-tumor T cell response which are then susceptible to later reinvigoration with ICIs." (PMID 38022659, 2023). "For instance, TYRP1-directed CAR T cells effectively controlled tumor growth in xenograft models, and CSPG4-targeted CAR T cells demonstrated potent cytotoxicity and feasibility for clinical-scale mRNA-based manufacturing." (PMID 41516067, 2025). "Overall, tumor samples from 207 potential participants were centrally prescreened for TYRP1 expression." (PMID 38577337, 2024). "Additional anti-Tyrp1 injections, when necessary, are done on days 5, 7, 9, 11, 13, and 15 post-tumor challenge." (PMID 38805560, 2024). "By reducing the criteria to 50% of total tumor cells with 3 + TYRP1 stain, 15 of the 38 patients would be eligible, ~40% of all screened patients (black line)." (PMID 38336975, 2024). "Rash as the second most common TRAE is likely an on-target (off-tumor) effect, due to targeting of TYRP1-positive melanocytes in the skin." (PMID 38577337, 2024). "This high frequency of TYRP1 overexpression in patient-derived cell lines is consistent with the levels observed in tumor biopsies." (PMID 38336975, 2024). "Using this system and a cut-off of 65% of total tumor cells with 3 + TYRP1 stain, 11 of the 38 patients screened would be eligible for the clinical trial (~29% of patients, dashed line)." (PMID 38336975, 2024). "In addition, this analysis suggested that a CD3 bi-specific antibody may not be the optimal therapeutic modality due to relatively low expression levels of the underlying genes in the tumor microenvironment, but other options such as TYRP1 CAR-therapy may prove viable." (PMID 39943991, 2024). "Even when tumor cells are opsonized with an ineffective monoclonal antibody (anti-Tyrp1) and enhanced through CRISPR interference (CRISPRi), poorly immunogenic solid tumors remain challenging." (PMID 38543240, 2024). "We showed that 96 hours after co-culture, TYRP1 CAR-T cells completely inhibited the growth of the three parental tumor cell lines, but this activity was lost in the TYRP1-knock-out cell lines." (PMID 38336975, 2024). "We found that both convalescent sera and anti-Tyrp1 suppressed tumor growth by days 11 and 13 relative to mIgG2a control." (PMID 37066426, 2024). "Moderately pigmented and heavily pigmented tumours had a significantly higher TYRP1 score than light tumours (p = 0.03 and p = 0.014, respectively)." (PMID 37240204, 2023). "We designed ACC by engineering genetic fusion of a cytokine (such as the IL-2 mimetic Neo2/15) on the C-terminus of the constant heavy chain of a tumor-specific anti-Tyrp1 antibody TA99." (PMID 36911698, 2023). "When looking at tumours that had two components with different levels of pigmentation, TYRP1 was usually higher in the darker areas than the lighter ones." (PMID 37240204, 2023). "Overall, VSV-IFNβ-TYRP1 is safe when given via IT injection and IV administration in patients who have less than 25% tumor burden in the liver." (PMID 38022659, 2023).
tumor (continued). "Overall, the doubling of CD47 KO metastases is suppressed ~4–5-fold by anti-Tyrp1 (Figure 2Biii), suggesting that anti-Tyrp1 drives tumor cell phagocytosis." (PMID 35454837, 2022). "Anti-Tyrp1 therapy of mice bearing CD47-deleted metastases nonetheless resulted in lower overall tumor burden even though mice succumbed with similar clinical symptoms as untreated controls." (PMID 35454837, 2022). "We showed that MEKi-mediated induction of melanosomal antigens, particularly TYRP1, combined with the administration of anti-tumor antibodies resulted in an enhanced therapeutic effect in both the BRAF-WT and BRAFV600E models." (PMID 33520112, 2021). "A similar trend was also observed in a syngeneic mouse model, where CD3xTrp1 (tyrosinase-related protein 1) was used to treat Trp1-positive B16F10 tumor cells." (PMID 33466732, 2021). "We found that TYRP1 was negatively correlated with CD8A expression while knockdown of TYRP1 promoted the expression of HLA-A, B, and C in tumor cells." (PMID 33869027, 2021). "Unfortunately, the efficacy of monotherapy with the tumor-antigen specific antibody IMC-20D7S (Anti-TRP1/TYRP1 monoclonal antibody) was limited in clinical trials, though it was well tolerated." (PMID 30786924, 2019). "Functionally, the mechanisms used by two melanoma‐specific lncRNAs (SAMMSON and TYRP1) to promote tumor growth were recently described." (PMID 30499222, 2019). "The combination of 17-AAG and Tyrp1-specific CD4+ T cells treated mice showed significantly higher survival at Day 40 after tumor challenge when compared with Tyrp1-specific CD4+ T cells alone (P<0.05)." (PMID 29481571, 2018). "In vivo, the combination of 17-AAG and cellular immunotherapy directed against Tyrp1 enhanced the inhibition of tumor growth compared to either therapy alone." (PMID 29481571, 2018). "In clinical studies, tyrosinase activity and TYRP1 expression have been shown to correlate inversely with the tumor stage." (PMID 28410220, 2017). "Microarray data were validated by real-time PCR measurement of TYRP1 mRNA expression in the skin metastases (N=13) of the training population." (PMID 22045183, 2011). "Given the involvement of Gpnmb and/or Tyrp1 in areas such as immunology and tumor development and progression, these strains are also important in other research fields." (PMID 17608931, 2007). "In MUM, the main challenge is finding truly tumor-restricted surface targets—because melanocytic differentiation antigens (e.g., TYRP1, GD2, B7-H3, HER2) are variably expressed on normal eye and skin tissue—yet several pre-clinical programs are beginning to address this gap." (PMID 41598579, 2026). "However, with 20D7SL-BBz CAR, tumor control is more modest and TYRP1 expression is maintained in the tumors, highlighting the presence of other resistance mechanisms (bottom)." (PMID 38336975, 2024). "Our results show that high TYRP1 overexpression is required to achieve detectable surface expression, allowing us to use the antigen density threshold as a mechanism to discriminate between tumor and normal tissues." (PMID 38336975, 2024). "In this work, we propose to target TYRP1 with CAR-T cell therapy as a strategy to decrease the potential on-target off-tumor toxicity through selective action against TYRP1 over-expressing cells and increase the antitumor activity via antigen-binding–mediated primary and secondary T-cell signaling." (PMID 38336975, 2024). "For anti-Tyrp1 and mouse IgG2a isotype control treatments, mice were treated intravenously or intraperitoneally with 250 μg with antibody on days 4, 5, 7, 9, 11, 13, and 15 after tumor challenge." (PMID 38805560, 2024). "Preclinical studies show TYRP1-TCB to have potent anti-tumor activity." (PMID 38577337, 2024). "Importantly, CD47 KO tumor nodules treated with anti-Tyrp1 show many F4/80-positive cells that are round in morphology and contain a single large nucleus plus some melanization." (PMID 35454837, 2022).